MMP7 (matrix metallopeptidase 7)
Diseases named in the same sentence as MMP7 in open-access papers (continued):
Sharing a sentence is not in itself a finding about the gene and the disease.
colon carcinoma (continued). "Moreover, both in vitro and in vivo studies have shown that blocking the activity of matrix metalloproteinases (MMPs) that are induced selectively by M3R activation, i.e., MMP1 and MMP7, also impedes colon cancer growth and progression." (PMID 33450835, 2021). "In MSS tumours, ETV4, along with the β-catenin, induced MMP7 in intestinal and colon cancer cells." (PMID 34824625, 2021). "Because secreted MMP-7 might play a role in the pathogenesis of early-stage colon tumors, we measured its form using an ELISA kit and conditioned medium from BFT-treated cells." (PMID 34769248, 2021). "Additionally, MMP7 was initially validated as a precancerous potential biomarker to prevent colon carcinoma." (PMID 31937294, 2020). "Indeed, SDC2 acts as a docking receptor for pro-MMP-7 in colon cancer cells, promoting pro-MMP-7 processing into the active MMP-7, and subsequent cleavage of MMP-7 substrate E-cadherin, which, in turn, results in enhanced cell migration." (PMID 32916872, 2020). "In the present study we analyzed whether polymorphisms rs28366003 in MT2A, rs1799750 in MMP-1, rs243865 in MMP-2, rs11568818 in MMP-7 and rs2252070 in MMP-13 genes are associated with the risk of breast, lung or colon cancer among polish subjects." (PMID 32765800, 2020). "In addition, we manipulated expression of SREBPs in colon cancer cell lines, and found that SREBP1 expression is associated with invasion, metastasis and angiogenesis; Finally, we demonstrated that SREBP1 induced MMP7 expression via the NF-κB pathway." (PMID 31299935, 2019). "This is consistent with prior studies of colon cancer, that also have indicated that MMP-7 could predict a more aggressive phenotype of colon cancer and correlate negatively with patient survival." (PMID 31200666, 2019). "We previously showed that syndecan-2 directly interacts with pro-MMP-7 and may contribute to processing it into active MMP-7 in colon cancer cells." (PMID 31337828, 2019). "Additionally, the application of MMP7 to colon cancer-bearing nude mice enhanced tumour metastasis and MMP9-deficient mice were protected against tumour metastasis." (PMID 29631554, 2018). "Higher metastatic potential is correlated with elevated matrix metalloproteinase-7 (MMP-7) expression in human colon cancer cells; less invasive colon cancer cells, such as Caco2 and HT29 cell line, present low MMP-7 expression level and high NOX1 and AMPK phosphorylation levels." (PMID 28626501, 2017). "Furthermore, MMP7 is known to regulate homotypic adhesion of colon cancer cells and enhance their metastatic potential." (PMID 25686828, 2015). "A study by Witty et.al., demonstrated that MMP7 knockdown clones derived from the colon cancer cell line SW620 do not form tumors as efficiently as the corresponding vector controls in orthotopic xenografts of colon cancer." (PMID 25875355, 2015). "MMP7 levels are increased in colon cancer tissues and in the serum of colon cancer patients." (PMID 25875355, 2015). "Moreover, activated MMP-7 can enhance syndecan-2 extracellular shedding to produce the soluble form of syndecan-2 in colon cancer cell conditioned media." (PMID 25686828, 2015). "MMP-7 is crucial for the invasion and metastasis of colon cancer." (PMID 25136657, 2014). "Furthermore, in human colon cancer cell lines, activation of muscarinic receptors results in substantial increases in MMP-7 expression." (PMID 24518611, 2014). "Activation of Rac1-ERK pathway and consequent upregulation of MMP-7 production may contribute to the function of radixin in the regulation of colon cancer cell invasion." (PMID 25136657, 2014). "Additionally, in the Min (multiple intestinal neoplasia) mouse model, gene knockout of MMP-7 significantly reduced colon cancer multiplicity and tumor size, thereby highlighting the role of MMP-7 in tumorigenesis." (PMID 24518611, 2014). "The increased MMP-7 expression correlates with malignant progression of human colon cancer." (PMID 23970935, 2013).
colon carcinoma (continued). "Expression of MMP7 was one of the significant predictors of lower patient survival, and MMP7 were significantly related to liver metastasis in colon cancer indicating that MMP7 overexpression appears to be a biological marker of aggressive phenotype in colon carcinoma." (PMID 24143235, 2013). "Lycopene also decreases MMP-7 expression in colon cancer cells." (PMID 23970935, 2013). "Additionally, MMP-7 expression seems to correlate with the metastatic potential of colon cancer cells." (PMID 22159423, 2012). "Our results further suggest that K-rasG12D-mediated ADM utilizes a PKCι-MMP-7 signaling pathway, and that, similar to lung and colon cancer, PKCι may play a promotive role in the initiation of PDAC." (PMID 22359542, 2012). "MMP7, however, has consistently been found to be relevant in colon cancer and its animal models." (PMID 21991341, 2011). "Although it has been suggested that the presence of Paneth cells in colon cancer is a fortuitous consequence of the Wnt pathway activation, it is interesting to note that Mmp7 up-regulation, as observed in our samples, has been correlated with metastasis and apoptosis resistance in cancer." (PMID 20459814, 2010). "To test this hypothesis, we examined the ability of TAM to decrease MMP7 activation in the ERβ-positive colon cancer cell line HT29." (PMID 19785773, 2009). "Besides overexpression of MMP7, a known β-catenin-dependent target gene in colon cancer, the results show an overexpression of MMP1, MMP3, MMP11, MMP12 and MMP13 in desmoid tumours compared to normal fibroblasts (fascia tissue)." (PMID 15054469, 2004). "In the case of CAC-associated MMPs (Mmp7, Mmp13) revealed in this study, focal high expression of Mmp7 was previously observed in CAC-related dysplastic lesions and its overexpression was associated with tumor growth, metastasis, and worse overall survival in patients with colon cancer." (PMID 36901742, 2023). "Indeed, the abilities of S2-FE to inhibit MMP-7 activity and the tumorigenic activities of colon cancer cells suggest that these peptides could potentially serve as effective anticancer drugs for colon cancer." (PMID 35682569, 2022). "MMP7 is a stromal lysin protein playing important roles in immunity, apoptosis, angiogenesis, and coagulation and is highly expressed in cancers of various types, including gastric cancer, uveal melanoma, and colon cancer, resulting in infiltration and metastasis of tumor cells." (PMID 36059641, 2022). "In addition, MMP7 promotes cell proliferation of lung adenocarcinoma cells and colon cancer cells." (PMID 33152225, 2021). "Since it is known that MMP-7 is localized at invasive front in colon cancer cells, syndecan-2 could immobilize pro-MMP-7 to restrict its range of action and regulate the processing of pro-MMP-7 to further regulate degradation of ECM and cell adhesion molecules." (PMID 31337828, 2019). "In SW480 and HCT116 human colon cancer cells, these processes result in decreased regulation of target β-catenin/TCF genes such as c-myc, MMP-7, and plasminogen activator urokinase." (PMID 36837487, 2023). "Auraptene has been reported to suppress matrix metalloproteinase (MMP)-2, MMP-7, and MMP-9 expression in human colon cancer cells, as well as MMP-2 and MMP-9 activity, to inhibit the migration and invasion of cancer cells." (PMID 37447286, 2023). "For example, matrix metalloproteinase-7 (MMP-7) binds to the extracellular domain of SDC2 and subsequently undergoes activation in colon cancer cells." (PMID 35682569, 2022). "Together, these data suggest that modifying S2-P by replacing an acidic amino acid in the vicinity of Tyr 51 enhanced the interaction with pro-MMP-7 and thereby inhibited MMP-7 activity and the cancer activities of colon cancer cells." (PMID 35682569, 2022).
colon carcinoma (continued). "A recent study showed that FGF-1/-3/FGFR4 signaling in CAF promotes tumor progression in colon cancer through ERK and MMP-7, inducing angiogenesis and cell proliferation, which suggests a crucial role of CAF and FGF signaling in colorectal cancer." (PMID 33946534, 2021). "Five SNPs, rs1799750 in MMP-1, rs243865 in MMP-2, rs11568818 in MMP-7, rs2252070 in MMP-13 and rs28366003 in MT2A has been studied in various cancers including breast, lung and colon cancer, but results were ambiguous." (PMID 32765800, 2020). "Cancer-by-cancer, lung squamous (LUSC) has two MMPs with sensitivities over 95% (MMP11 and MMP12), colon cancer (COAD) has three over 94% (MMP11, MMP28, and MMP7), and esophageal cancer (ESCA) has two over 94% (MMP11 and MMP12)." (PMID 31200666, 2019). "In vitro, SREBP1 over-expressed in colon cancer cell lines HT29 promoted angiogenesis in endothelial cells, increased ROS levels, phosphorylation of NF-κB-p65 and increases MMP7 expression." (PMID 31299935, 2019). "Luminex based expression analysis revealed a significant overexpression of MMP7 and an overexpression of MMP10 and MMP12 in the sera of colon cancer patients compared to the healthy control group." (PMID 27431388, 2016). "After having confirmed differences in the expression of MMP7, MMP10 and MMP12 concentrations in colon cancer patients ́ serum samples and serum samples of a healthy control group we correlated these results with patients’ overall survival." (PMID 27431388, 2016). "Expression patterns of MMP7, MMP10 and MMP12 in colon cancer patients ́ sera are different compared to serum specimens of healthy individuals." (PMID 27431388, 2016). "Taken together our results propose that MMP7, MMP10 and MMP12 are increased in sera of colon cancer patients when compared to healthy donors and MMP12 seems to play a role in vascular invasion." (PMID 27431388, 2016). "In the present study we investigated the expression of MMP7, MMP10 and MMP12 in serum specimens in a homogenous collective of colon cancer patients with regard to clinicopathological characteristics and patients ́ prognosis." (PMID 27431388, 2016). "The present investigation yielded MMP7, MMP10 and MMP12 serum levels in a homogenous group of colon cancer patients to be adverse prognostic molecular markers exerting valid multiplex bead-based immunoassay - technologies." (PMID 27431388, 2016). "The expression of MMP7, MMP10 and MMP12 were determined in serum samples of 78 colon cancer patients and 38 serum samples of healthy individuals using Luminex 100TM technology." (PMID 27431388, 2016). "In summary, our results imply a significant influence of serum MMP7, MMP10 and MMP12 in human colon cancer dissemination with considerable impact on overall survival." (PMID 27431388, 2016). "We aimed to investigate the relationship of expression of matrix metalloproteinase-7 (MMP-7), tissue inhibitor of metalloproteinase-1 (TIMP-1) and cyclooxygenase-2 (COX-2) in colon cancer and its predecessor colon polyp." (PMID 29201696, 2015). "A previous report demonstrated that PRL3 activity regulates MMP7 expression via the PI3K/AKT and ERK signaling pathway in the colon cancer derived cell line DLD1." (PMID 25875355, 2015). "In the current study, we investigated the regulatory roles of NOX in MMP-7 expression and AMPK activity by comparing invasive behaviors of HT29 and SW620 colon cancer cells." (PMID 26116564, 2015). "Under basal conditions, less invasive human colon cancer cells (HT29 and Caco-2) showed low MMP-7 expression but high NOX1 expression and AMPK phosphorylation." (PMID 26116564, 2015). "Since radixin can induce Rac1 and ERK1/2 activation these results suggest that radixin influences MMP-7 production via Rac1 and ERK1/2 activation in colon cancer cells." (PMID 25136657, 2014). "In summary, our present work demonstrates that radixin can promote the invasion of colon cancer cells by activating Rac1-ERK pathway and upregulating MMP-7 production." (PMID 25136657, 2014).
colon carcinoma (continued). "Previously, in human colon cancer cell lines, we showed that of the ~25 known MMP genes, acetylcholine treatment selectively induced robust transcription of MMP1, MMP7 and MMP10." (PMID 23617763, 2013). "In a systematic analysis of MMP gene transcription, we identified the same three MMP genes [MMP1 (functional human homologue of mouse MMP13), MMP7 and MMP10] as target genes for acetylcholine-M3R activation in human colon cancer cell lines." (PMID 23617763, 2013). "Regarding the substantial inhibitory effects of HS7 on Wnt/β-catenin signaling and its downstream MMP7 and MT1-MMP mRNAs expression, it indicates the potential use of HS7 as anti-invasion and antiangiogenesis agent against colon cancer cells." (PMID 21423639, 2011). "Matrix metalloproteinase 7 (MMP7), a metallohydrolase involved in the development of several cancers, is downregulated in the ApcMin/+ colon cancer mouse model following sulindac treatment." (PMID 21991341, 2011). "PEA3 has been established as an important regulator of cell invasion in colon cancer and gastric adenocarcinoma cells through regulation of MMP-1 and MMP-7 respectively." (PMID 21143918, 2010). "Levels of WNT target gene mRNAs were markedly increased in colon tumor tissues compared with colon non-tumor tissues, especially Mmp7 and Axin2 mRNAs." (PMID 36765047, 2023). "Moreover, HT29-SDC2 cell showed increased cell surface localization of MMP-7, confirming that SDC2 regulates the cell surface localization of MMP-7 in colon cancer cells." (PMID 35682569, 2022). "Interestingly the farnesoid X receptor (FXR) has been shown to act as a transcriptional repressor of MMP7 in colon cancer cells, and an inverse relationship has been observed between FXR and MMP7 expression." (PMID 33536476, 2021). "For instance, MMP-7 (matrilysin, a metalloproteinase with prometastatic function) could increase the OXA resistance of colon cancer cells by decreasing the Fas receptor that stimulates cell apoptosis." (PMID 33807355, 2021). "The aim of this study was to investigate association of polymorphisms rs1799750 in MMP-1, rs243865 in MMP-2, rs11568818 in MMP-7, rs2252070 in MMP-13 and rs28366003 in MT2A, together with serum Zn level, with occurrence of breast, lung and colon cancer in Poland." (PMID 32765800, 2020). "Interestingly, AvrA activates the expression of the STAT3 target genes MMP7 (matrix metalloproteinase-7) and SOCS3 (suppressor of cytokine signaling 3) in a colon cancer mouse model." (PMID 31611869, 2019). "We thus further analyzed the data from TCGA and showed that HPSE is positively correlated with the expression of MMP1 in colon cancer (r = 0.3476, p < 0.0001) and rectal cancer (r = 0.3428, p < 0.0001), but not MMP7, MMP10, and MMP13." (PMID 31001480, 2019). "In a previous study, inhibition of hyaluronan (HA) synthase-2 (HAS2), a biosynthetic enzyme of hyaluoran which is known as one of MMP7 regulators, was shown to decrease MMP7 expression under the condition of HAS2 inhibition and consequently inhibit the invasion ability of colon cancer cells." (PMID 28757546, 2017). "In colon cancer cells, this molecular switch from NOX1 to NOX2, together with NOX2-derived ROS, increases MMP-7 expression by the deactivation of AMPK, and the TPA-induced phenotype can be reverted by NOX2 but not NOX1-targeting siRNA, suggesting that NOX2 activity induces an invasive phenotype." (PMID 28626501, 2017). "HspB5, MMP7 and E-cadherin were validated to be differentially expressed when comparing colonic tumor tissue and adjacent nontumor samples from CRC patients." (PMID 28796798, 2017). "Moreover overexpression of MMP7, MMP10 and MMP12 in colon cancer patients ́ sera displayed a significantly impaired overall survival." (PMID 27431388, 2016). "However divergent evidence exists that - opposing to MMP7 and MMP10 - MMP12 diminishes colon cancer growth in vitro and has a favorable impact on overall survival in colorectal cancer patients." (PMID 27431388, 2016).
colon carcinoma (continued). "A role and implication of expressions of MMP-7, COX-2 and TIMP-1 in colon cancer is predicted." (PMID 29201696, 2015). "Finally, we identified that radixin promoted invasion and migration of colon cancer cells by activating Rac1-ERK pathway and by increasing MMP-7 production." (PMID 25136657, 2014). "One hint might be the observed cleavage of Laminin5, since this process is in most part mediated by MMP-1 and MMP-7, and only in little part by MMP-9, in colon cancer." (PMID 24913355, 2014). "Therefore, in parallel to analyses of IGF-1R, IGF-1/2 and MMP-7 mRNA expression in tissue from colorectal cancer patients, we assessed the effects of the IGF-1R-inhibitory compound PPP in four colon carcinoma cell lines." (PMID 22159423, 2012). "Moreover, lycopene exhibited promising in vitro anticancer activity against human colon cancer cells (HT-29) by inhibiting the phosphorylation of Akt, glycogen synthase kinase-3β (GSK-3β), and ERK 1/2 proteins and by suppressing MMP-7 expression, thus preventing metastasis and angiogenesis." (PMID 39478959, 2024). "Compared to S2-P, S2-FE was better able to inhibit the SDC2–MMP-7 interaction, the cell surface localization of MMP-7, the gelatin degradation activity of MMP-7, and the cancer activities (cell migration, invasion, and colony-forming activity) of human HCT116 colon cancer cells in vitro." (PMID 35682569, 2022). "For example, in human colon cancer cell lines SNU-C4, HT-29, and H508, administration of atropine, muscarinic receptors inhibitor eradicated SNU-C4 cell migration and HT-29 invasion; however, H508 cell migration entails the activation of MMP7 via EGFR and ERK signaling pathways." (PMID 36614038, 2022). "It was also reported that the colon cancer cells invasion was regulated via ERK/c-Fos/MMP-7 signaling axis, and the metastasis of colon cancer cells may be treated by the suppression of the ERK/c-Fos/MMP-7 signaling pathway." (PMID 35641944, 2022). "Furthermore, overexpression of MMP7, MMP10 and MMP12 in colon cancer patients ́ sera correlates with a dismal prognosis and may help to stratify patients into different risk groups." (PMID 27431388, 2016). "Thus, expression of β-catenin, Cyclin D1, and Mmp7 remained high in adenomatous polyps compared to normal colon, and was unaffected by SPI3d or SPI treatment, although SPI increased cleaved PARP and Caspase–3 in Pirc colon tumors, indicative of apoptosis induction." (PMID 35159382, 2022). "Interestingly, a study by Heerdt and colleagues demonstrated that the instrinsic ΔΨm in colon cancer cells significantly correlated with invasive potential and expression of the pro-angiogenic vascular endothelial growth factor (VEGF) and the matrix metalloproteinase MMP7." (PMID 25471892, 2014). "MMP7 has been shown to be important for accelerating cancer invasion and metastasis in multiple tissues, but does not seem to be necessary for invasion or fibrosis of colon cancer, in which Smad4-dependent transforming-growth-factor (TGF)-β family signaling is blocked." (PMID 25424420, 2014). "Moreover, knockdown of LEF1 expression could significantly decrease the levels of MMP-2 and MMP-9 protein, but not MMP-7 protein in shLEF1 cells compared to that of shNC colon cancer cells." (PMID 24098538, 2013). "We found that knockdown of LEF1 expression suppressed MMP2 and MMP-9 expression, but not MMP-7, indicating that the selective modulation of MMPs by LEF1 could have the biological significance in colon cancer progression." (PMID 24098538, 2013).